TF (transferrin)
Diseases named in the same sentence as TF in open-access papers (continued):
Sharing a sentence is not in itself a finding about the gene and the disease.
glioma (continued). "Dual-targeting daunorubicin Liposomes were developed by conjugating with p-aminophenyl-alpha-D-manno-pyranoside and transferrin for transporting drug across the BBB and then targeting glioma cells." (PMID 40944840, 2025). "The overexpression of transferrin (Tf) and lactoferrin (Lf) receptors on BBB endothelial cells and glioma cells presents an opportunity for targeted drug delivery." (PMID 39409919, 2024). "Pseudolaric acid B has the ability to upregulate TF and its receptor to enhance iron import, thus activating NOX4 and arousing ferroptosis in glioma cells." (PMID 39309434, 2024). "Another dual-targeted approach was developed to treat glioma with DOX, combining a magnetic targeting Fe3O4 and molecular brain targeting using transferrin, whose receptor is overexpressed on glioma cells and on the vascular endothelial cells of the BBB." (PMID 35740342, 2022). "The synergistic effects of a triple conjugate targeting system, consisting of CDs conjugated to transferrin and the chemotherapeutic compounds epiburicin and TMZ, on pediatric and adult glioma cells, have also been investigated in vitro." (PMID 35715639, 2022). "In a similar study, conjugation of the glioma-targeting ligand transferrin with the CPP octa-arginine (R8) enhanced uptake and antiproliferative effects in U87 MG and GL261 glioma cell lines." (PMID 35715639, 2022). "Tf-ELE/CTX@BLIP were prepared by conjugating liposomes with transferrin (Tf) and embedding the cell membrane proteins of RG2 glioma into liposomes, which exhibited high efficacy in infiltration of the BBB and targeting of glioma cells." (PMID 34565383, 2021). "The cellular uptake demonstrated that TF bound well to the bEnd.3 cells and C6 cells, for both the first stage to deliver the drug across the BBB and the second stage to target glioma." (PMID 25289086, 2014). "In the present study, a dual-targeting LP conjugated with transferrin and RGD was generated for glioma-targeting therapy." (PMID 25289086, 2014). "In all gliomas cell lines (U251MG, U87MG, A172, and T98G) the 99mTc-TF uptake was significantly higher than 99mTc-sestamibi." (PMID 25436147, 2014). "The 99mTc-TF uptake, ranging between ~21% and 22% in the four studied cell lines, was higher than 99mTc-MIBI in the four studied glioma cell lines (16% to 18%)." (PMID 25436147, 2014). "Thus, 99mTc-TF may be superior to 99mTc-MIBI for glioma imaging in vivo." (PMID 25436147, 2014). "In conclusion, the present study has demonstrated a targeted delivery system for glioma therapy, RGD/TF-LP." (PMID 25289086, 2014). "Kawabata and his research team recently have evaluated sodium borocaptate, containing transferrin targeting liposomes, which were administered i.c. by CED, as potential boron delivery agents for neutron capture therapy of F98 glioma bearing rats." (PMID 23152799, 2012). "Transferrin-conjugated improved tumor targeting of PTX-loaded NPs and showed synergistic effects through transferrin-mediated endocytosis and high biocompatibility in a rat glioma model." (PMID 40860814, 2025). "The Nio-based delivery system introduces a dual-targeting strategy by combining passive BBB penetration (via P-gp inhibition by nonionic surfactants) and active glioma cell targeting (via TF conjugation)." (PMID 40140588, 2025). "Because of the inherent ability of folate and transferrin separately in crossing the BBB and targeting gliomas, the dual-targeting decorated liposome loading Dox finally exhibited excellent antitumor effect by significantly increasing mice survival time and decreasing tumor volume, among others." (PMID 39911305, 2025). "Their results showed that the transferrin (Tf)-modified PAMAM displayed improved targeting capability in homing to glioma cells when compared to non-modified PAMAM." (PMID 39065339, 2024). "Conjugation of gemcitabine-CDs to transferrin showed the highly selective destruction of SJGBM2 glioma cells over non-cancerous HEK293 cells in vitro." (PMID 35715639, 2022).
glioma (continued). "Results showed that the transferrin conjugated samples were more cytotoxic to the glioma cell lines compared to non-transferrin conjugates and that the triple systems were more cytotoxic than the dual systems." (PMID 35715639, 2022). "Herein, transferrin (Tf)-decorated niosomes with integrated magnetic iron oxide nanoparticles (MIONs) and quantum dots (QDs) were formulated (PEGNIO/QDs/MIONs/Tf) for efficient imaging of glioma, supported by magnetic and active targeting." (PMID 33925347, 2021). "pSiNPs functionalised with transferrin and CSC-targeting moieties might allow for broader migratory inhibition of the different glioma cell subpopulations." (PMID 33637089, 2021). "TF-LP is distributed throughout the whole brain without selectivity, while RGD/TF-LP is distributed in the glioma of the brain more than TF-LP, revealing an effective and precise target for this type of brain cancer." (PMID 25289086, 2014). "The increased uptake by the glioma may be due to the enhanced penetration of the RGD and TF when the LPs diffused to the glioma by an enhanced permeability and retention effect." (PMID 25289086, 2014). "The results showed higher 99mTc-TF uptake, thus suggesting that 99mTc-TF could be superior to 99mTc-MIBI for glioma imaging." (PMID 25436147, 2014). "Transferrin-functionalized PEG-PLA nanoparticles (~150 nm) increased resveratrol uptake in glioma cells (C6 and U87), reduced tumor volume, accumulated in brain tumors, and extended survival in glioma-bearing rats, suggesting their potential as targeted glioblastoma therapy." (PMID 40572668, 2025). "The control and Cur-solution groups presented high heterogeneity and visible mitotic figures, indicating high malignancy, whereas the TF-Cur-Nio group presented fewer tumor cells, lower cell density, and no visible mitotic figures, suggesting a better anti-glioma effect." (PMID 40140588, 2025). "Moreover, glioma cells as well as endothelial cells of the BBB express high amounts of low-density lipoprotein receptor-related protein-1 (LRP1), which mediates the transcytosis of multiple ligands across the BBB (such as lactoferrin, melanin, transferrin)." (PMID 39194524, 2024). "Despite the mainstream use of pSiNPs for drug loading, such as doxorubicin, we found that blank pSiNPs functionalised with transferrin to aid glioma-specific cell entry, are not cytotoxic, and can be effective at disrupting U87 cell migration across narrow physical confinements." (PMID 33637089, 2021). "In addition, 99mTc-TF was more lipophilic than MIBI and thus could enter easier than MIBI in glioma cells." (PMID 25436147, 2014). "It is proposed that the targeting of glioma can be achieved in the following two steps: The TFR that is overexpressed in the BBB may aid the LP to cross the BBB efficiently, while the RGD and TF enhance the targeting migration and accumulation of LPs to the αvβ3 integrin-expressing tumor." (PMID 25289086, 2014). "Thus, the dual-targeting LP conjugated with TF and RGD may have the potential to serve as a drug delivery system in glioma therapy." (PMID 25289086, 2014). "In glioma patients we found that 99mTc-TF uptake was not related to the MRP5 immunohistochemical expression; consequently, this might be another reason explaining the higher 99mTc-TF uptake in the studied glioma cell lines." (PMID 25436147, 2014).
Obesity (55 papers, 2013 to 2025). Accumulation of substantial excess body fat. "We also found that other obesity-related traits were associated with increased ferritin and decreased transferrin saturation." (PMID 40722713, 2025). "After adjusting for obesity-related traits, we found that serum iron, ferritin, and transferrin saturation were associated with increased risks of MASLD in both iron homeostasis datasets." (PMID 40722713, 2025). "Specifically, overweight/obesity was negatively associated with dietary iron intake, serum iron levels, and transferrin saturation but positively associated with TIBC." (PMID 41141252, 2025). "According to obesity status, serum hepcidin (positively) and transferrin (negatively) were associated with changes in iSAT and iVAT in subjects without obesity." (PMID 36902180, 2023). "The impaired iron-handling ability of AT macrophages in obesity leads to accumulation of AT iron and deficiency of hepatic iron, along with elevated ferritin and transferrin." (PMID 37029208, 2023). "Our findings suggest that iron-related biomarkers like ferritin and transferrin are significantly associated with separate obesity or separate metabolic abnormalities." (PMID 36091521, 2022). "In our analysis, the persistent positive association between TIBC and BMI/obesity risk aligns with this physiological role: during iron-restricted states, the liver upregulates transferrin synthesis to enhance iron uptake as a compensatory mechanism, leading to elevated TIBC." (PMID 41141252, 2025). "Transferrin, which is responsible for iron systemic transport, is associated with insulin resistance; elevated transferrin levels have been observed in many cohorts with obesity and chronic inflammatory state, predisposing to insulin resistance." (PMID 39941760, 2025). "Obesity and inflammation may cause pathological alterations in iron metabolism and transferrin function, which can eventually contribute to the dysregulation of insulin sensitivity." (PMID 39941760, 2025). "They further suggest that TF activity may alter methylation status and that methylation status may impact TF activity at differentially methylated sites associated with obesity." (PMID 37188674, 2023). "At a cellular level, many of the TF families linked to obesity-associated DNA methylation variations – AP1, KLF, SOX and ETS – have established or emergent roles in adipocyte biology and metabolism, connecting disease-related DNA methylation variations to potential pathogenic pathways." (PMID 37188674, 2023). "Thus establishing that the binding motifs of methylation-sensitive transcription factors are enriched for methylation changes associated with obesity that influence TF-target gene co-expression relationships." (PMID 37188674, 2023). "Moreover, it seems that the strength of the associations of ferritin and transferrin with the coexistence of both metabolic abnormalities and obesity was stronger than that for obesity alone (i.e., the ORs of MHO were lower than those of MUO)." (PMID 36091521, 2022). "Moreover, several studies have reported that transferrin and soluble transferrin receptor (sTfR) are associated with obesity, metabolic syndrome and other cardiovascular risk factors in adults and children." (PMID 30755213, 2019). "Since obesity is associated with chronic low-grade inflammation, acute phase protein levels, including albumin and transferrin, might be altered." (PMID 29324643, 2018). "In addition, the ZNF143 TF was previously posited as a biomarker for obesity-associated T2D." (PMID 38781157, 2024). "In both of the iron homeostasis datasets, the effect directions of obesity-related traits on iron, ferritin, and transferrin saturation were consistent." (PMID 40722713, 2025). "The study highlights that ID is more common in children diagnosed with obesity, and serum iron and transferrin saturation are better indicators of ID than serum ferritin or TIBC." (PMID 40298814, 2025).
Obesity (continued). "In conclusion, elevated levels of dietary iron intake, serum iron concentration, and transferrin saturation were linked to a lowered risk of overweight/obesity, suggesting that maintaining adequate iron status may play a crucial role in preventing and managing obesity." (PMID 41141252, 2025). "Transferrin saturation was lower in women with obesity at 12 and 28 GW (12 GW 23.9%, 24.5%, 30.3%, P = 0.016; 28 GW 13.2%, 17.7%, 17.2% P < 0.001, obesity, overweight, and normal weight, respectively)." (PMID 40886951, 2025). "Changes in iron metabolism in children and adolescents with obesity are characterized by decreased serum iron levels, a reduced transferrin saturation index, and elevated ferritin and hepcidin levels." (PMID 41465437, 2025). "Children with overweight and obesity had low serum iron and transferrin saturation but elevated serum ferritin with normal total iron-binding capacity." (PMID 40298814, 2025). "Cross-sectional studies have shown that transferrin saturation negatively correlates with BMI and is lower in men and women with obesity and an expanded waist circumference than in those with obesity but with a smaller waist circumference." (PMID 37029208, 2023). "This review further reported a tendency for higher ferritin concentration and lower transferrin saturation in obesity, which all agree with our current study results." (PMID 37242155, 2023). "Specially, children with obesity had significantly lower Fe, transferrin saturation, and total-iron binding capacity along with higher ferritin, soluble transferrin receptors and hepcidin-25 than children of normal weight." (PMID 38150411, 2023). "After controlling for covariates, women taking opioids had higher odds of Class II (OR = 1.6, 95% CI = 1.1–2.3) or III obesity (OR = 1.6, 95% CI = 1.1–2.5), and lower levels of serum folate, iron, and transferrin saturation." (PMID 37111110, 2023). "A decreased level of serum iron in the plasma pool will result in low transferrin saturation, as observed in women with obesity." (PMID 37242155, 2023). "Of these ten studies, seven showed that obesity groups had increased mean-hemoglobin concentrations; six had raised serum ferritin; and four had reduced transferrin saturation." (PMID 36902180, 2023). "Our findings of lower serum iron and transferrin saturation in women with obesity align with reports from a systematic review showing that serum iron and transferrin saturation are lower with high BMI." (PMID 37242155, 2023). "Significant differences were found between participants with obesity and those with overweight in the levels of transferrin saturation, vitamin B12, HDL-C, and CRP." (PMID 36498548, 2022). "Substantial clinical evidence emphasizes the upregulation of TF pathway in states of obesity and MetS." (PMID 35406450, 2022). "The median level of iron was (p = 0.002) lower in participants with overweight/obesity (56.0 mcg/dL) than in participants with normal weight (68.0 mcg/dL), as well as the transferrin-saturated level of l 15.8% vs. 19.4%." (PMID 36498548, 2022). "In children 6 to 8 years of age, an abnormal neutrophil count was noted among children with severe obesity and an increased prevalence of abnormal ferritin/transferrin ratio began at 9 to 11 years of age, demonstrating how early obesity increases inflammation." (PMID 36292751, 2022). "Specifically, children with obesity had significantly lower iron, transferrin saturation and total-iron binding capacity along with higher ferritin, soluble transferrin receptors and hepcidin-25 than children of normal weight." (PMID 32808447, 2021). "Overexpression of Sna TF genes specifically in the heart promotes whole-body leanness whereas their knockdown in the heart promotes obesity." (PMID 31725726, 2019). "Results support a positive relationship between obesity and inflammation, with mild disruptions to some iron markers such as serum iron and transferrin saturation." (PMID 23861932, 2013).
Obesity (continued). "After adjusting for confounding variables, weighted logistic regression analysis identified reduced odds of overweight/obesity with higher dietary iron intake (OR = 0.98, p = 0.026), serum iron (SI; OR = 0.98, p = 0.004), and transferrin saturation (TSAT; OR = 0.98, p = 0.003)." (PMID 41141252, 2025). "Several studies have explored the relationship between obesity and iron status during pregnancy, with many reporting that women with obesity tend to have lower iron status, as indicated by markers such as transferrin saturation (TSAT) and serum iron concentrations." (PMID 40886951, 2025). "Among the women with obesity-T2D, 57.7% had a transferrin saturation higher than 45%." (PMID 40895225, 2024). "In this study, a total of 265 candidate target genes were screened by integrating the information of DEGs and miRNA target genes in granulosa cells of PCOS patients with insulin resistance, among which 7 TF genes and five target genes closely related to obesity were identified." (PMID 36873932, 2023). "However, more research is needed to confirm the potential role of these bacteria in obesity regulation, and to provide more evidence for egg protein transferrin-derived peptides IRW and IQW in alleviating the adverse effects of obesity." (PMID 36232527, 2022). "Model 2 which included the variables “transferrin-saturated and CRP” instead of “iron and HDL-C”, respectively, showed similar results, with a significant positive association between the CRP and overweight/obesity (OR 1.39, 95% CI 1.10–1.76, p = 0.007)." (PMID 36498548, 2022). "SEPP1 concentration, GPX activity, and iron status biomarkers (serum iron, transferrin saturation, and hemoglobin concentration) were lower among individuals with overweight/obesity compared with individuals with normal weight, but these differences were not significant (p > 0.05)." (PMID 31597392, 2019). "However, despite the highest ferritin level in group C (the obesity group), transferrin saturation was the lowest (M = 30.65, SD = 1.39, P < 0.001)." (PMID 28116148, 2016). "Studies have reported that lower serum Fe concentrations and transferrin saturation were found in obese/overweight individuals, and a negative correlation between transferrin saturation and adiposity was also found in school children with obesity who aged between 9 and 13 years old." (PMID 38150411, 2023). "Children with obesity frequently develop IDA, exhibiting lower hemoglobin, iron, and transferrin saturation levels and higher ferritin and hepcidin concentrations compared with non-obese peers." (PMID 41465437, 2025). "Concurring with this data, we also observed increased plasma levels of ferritin and transferrin, higher TIBC, decreased transferrin saturation, and elevated RDW-CV values, which are considered typical hallmarks of obesity-related anemic states." (PMID 38238301, 2024). "Subjects with obesity also had increased hepatic-iron concentration, circulating ultrasensitive C-reactive protein (CRP), fasting triglycerides, serum uric acid, serum transferrin, and total iron-binding capacity (TIBC)." (PMID 36902180, 2023). "Accordingly, S1PR3, IQCG, and TF are common in HCL, aging, and CVD; ACSL1, THBD, and HNF4A are repeated in HTN, obesity, and CVD." (PMID 36035865, 2022). "Other possible reasons for heterogeneity were that low albumin was not the only susceptibility factor for SSI, obesity, age, low total lymphocyte counts, transferrin and combinations of these factors could all exerted an impact on SSI, and there were inconsistent factors among these studies." (PMID 28093079, 2017). "For example, in one systematic review, the authors reported that “children living with obesity had significantly lower levels of hemoglobin, iron, % transferrin saturation, and higher levels of ferritin and hepcidin than children without obesity”." (PMID 40568272, 2025).